PNPP1 (PNP pseudogene 1)
Gene: Processed pseudogene on chromosome 2 (76,258,034 to 76,258,897, reverse strand). Ensembl gene ENSG00000228209.
Diseases named in the same sentence as PNPP1 in open-access papers:
PNPP1 is named in the same sentence as 1 disease in open-access papers, as found by Europe PMC text mining. Sharing a sentence is not in itself a finding about the gene and the disease.
glioblastoma (1 paper, 2023). The most malignant astrocytic tumor (WHO grade IV).